PLEKHG4 (pleckstrin homology and RhoGEF domain containing G4)
Description:
Possible role in intracellular signaling and cytoskeleton dynamics at the Golgi.
Synonyms: PRTPHN1; DKFZP434I216; ARHGEF44; SCA4
Tractability: Antibody: its Gene Ontology location is reachable by antibodies, with medium confidence. PROTAC: ubiquitination databases record sites on it.
Gene: Protein-coding gene on chromosome 16 (67,277,510 to 67,289,499, forward strand). Ensembl gene ENSG00000196155.
Subcellular location (Human Protein Atlas): Cell Junctions
Pathways (Reactome):
Signal Transduction: CDC42 GTPase cycle; RAC1 GTPase cycle; RHOA GTPase cycle
Gene Ontology:
Molecular function: protein binding; guanyl-nucleotide exchange factor activity
Biological process: axon guidance; regulation of small GTPase mediated signal transduction
Cellular component: cytoplasm; cytosol; extrinsic component of membrane; plasma membrane
Genetic constraint (gnomAD): Loss-of-function variants: 81 observed, 135.49 expected, observed/expected ratio (o/e) 0.6, 90% interval 0.5 to 0.72. The upper end of that interval is the gene's LOEUF score, 0.72, which puts it in group 2 of 6, group 1 being the genes least tolerant of losing a copy. Missense variants: 1,298 observed, 1,561.7 expected, observed/expected ratio (o/e) 0.83, 90% interval 0.79 to 0.87. Synonymous variants: 570 observed, 663.94 expected, observed/expected ratio (o/e) 0.86, 90% interval 0.8 to 0.92.
Homologues: Orthologues: chimpanzee PLEKHG4 (99% identical), dog PLEKHG4 (82% identical), pig PLEKHG4 (81% identical), rabbit PLEKHG4 (79% identical), rat Plekhg4 (75% identical), mouse Plekhg4 (73% identical), guinea pig PLEKHG4 (57% identical), zebrafish plekhg4 (42% identical), tropical clawed frog plekhg4 (42% identical). Paralogues in human: PLEKHG4B (34% identical), ARHGEF40 (28% identical), TRIO (21% identical), KALRN (20% identical), KIAA1755 (16% identical), MCF2L (16% identical), MCF2 (16% identical), TIAM1 (14% identical), MCF2L2 (13% identical), TIAM2 (13% identical), PLEKHG1 (11% identical), VAV2 (11% identical), and 10 more.
Diseases named in the same sentence as PLEKHG4 in open-access papers:
PLEKHG4 is named in the same sentence as 10 diseases in open-access papers, as found by Europe PMC text mining. Sharing a sentence is not in itself a finding about the gene and the disease. The quoted sentences say what the papers report.
autosomal dominant spinocerebellar ataxia (5 papers, 2014 to 2023). "Plekhg4 was originally identified through its role in the pathology of autosomal dominant cerebellar ataxia (ADCA) in a Japanese population." (PMID 33923452, 2021).
Ataxia (3 papers, 2009 to 2021). Ataxia refers to impaired coordination of voluntary muscle movement. "PLEKHG4 is associated with Spinocerebellar ataxia, a neurodegenerative disease affecting cerebellar Purkinje cells." (PMID 33941312, 2021). "Heterozygous mutations in SLC33A1 have been associated with spastic paraplegia (SPG42) with ataxia in a single family, and likewise, missense mutations in PLEKHG4 have been implicated in dominant late onset forms of spinocerebellar ataxia in Japanese individuals." (PMID 25976027, 2015).
female infertility (1 paper, 2024). Diminished or absent ability of a female to achieve conception. "Through rare-variant and gene-based analyses in the UK Biobank, we additionally identified PLEKHG4 associated with female infertility and 50 genes for testosterone, including the first reported hormone-associated variants in some members of the hydroxysteroid dehydrogenase enzyme family." (PMID 38562841, 2024).
thyroid cancer (1 paper, 2025). "The overexpression of PLEKHG4 significantly promoted thyroid cancer cell proliferation, while its knockdown inhibited proliferation." (PMID 40426910, 2025). "Integrating these findings, the authors proposed a regulatory mechanism involving the UBE2O/PLEKHG4/RhoGTPases axis in thyroid cancer progression." (PMID 40426910, 2025). "The authors further examined the effects of PLEKHG4 on cell proliferation, migration, invasion, and epithelial–mesenchymal transition (EMT) by overexpressing or knocking down PLEKHG4 in thyroid cancer cells." (PMID 40426910, 2025). "Collectively, UBE2O modulates PLEKHG4 stability, which subsequently influences RhoGTPase activity, thereby driving thyroid cancer progression." (PMID 40426910, 2025). "PLEKHG4, in turn, activates RhoGTPases (RhoA, Cdc42, and Rac1), which promote the proliferation, migration, invasion, and EMT process of thyroid cancer cells." (PMID 40426910, 2025).
cancer (1 paper, 2023). A tumor composed of atypical neoplastic, often pleomorphic cells that invade other tissues. "However, the functions of UNC79, PLEKHG4, and ENSCAFG00845007156 and their associations with cancers have not yet been identified." (PMID 37760246, 2023).
PLEKHG4 also shares sentences with these, for which no sentence is quoted: cerebellar ataxia (1 paper); cerebellar disorder (1); neurodegenerative disease (1); Sensory axonal neuropathy (1); Spastic paraplegia (1).